F8 (coagulation factor VIII)
Diseases named in the same sentence as F8 in open-access papers (continued):
Sharing a sentence is not in itself a finding about the gene and the disease.
hemophilia A (continued). "The current standard of care treatment for severe hemophilia A and B (SHA and SHB) is the prophylactic intravenous replacement of coagulation factor VIII or IX (FVIII/FIX) to prevent spontaneous bleeding." (PMID 32918114, 2020). "Hemophilia A (OMIM #306700), an inherited bleeding disorder, harbors two such rearrangements at chromosome X (Xq28) involving the coagulation factor VIII (F8) gene." (PMID 31191618, 2019). "In the present study, we successfully produced F8+/− pigs by ICSI using xenogeneic sperm derived from the foetal F8−/Y cloned pigs, and then established a strain of haemophilia A pigs using these F8+/− pigs as founders." (PMID 29208927, 2017). "Recently, an ~150 kb deletion of Xq28 encompassing part of F8, FUNDC2, CMC4, MTCP1, and BRCC3 was reported in a child with severe hemophilia A, Moyamoya disease, and distinctive facial features." (PMID 25927380, 2015). "For example, coagulation factor VIII (FVIII) is normally expressed by liver sinusoidal endothelial cells, which are less abundant and challenging to target with vectors; therefore, gene therapy for hemophilia A primarily targets hepatocytes." (PMID 41511298, 2025). "That is to say he did not have a significant hemophilia A disease phenotype (blood coagulation factor VIII activities 69.1%)." (PMID 36845383, 2023). "Hemophilia A (Classical) and B (Christmas disease) are congenital bleeding disorders caused by a deficiency or complete absence of coagulation factor VIII (FVIII) or factor IX (FIX), respectively." (PMID 35804421, 2022). "The aim of this study was to evaluate the therapeutic effect of KPs for the treatment of osteoporosis in coagulation factor VIII (FVIII) gene knockout mice (F8KO), a model of hemophilia A. In this study, male F8KO mice at 20 weeks of age were orally administered different doses of KPs for 8 weeks." (PMID 35252176, 2022). "“Lentiviral gene therapy to the liver establishes stable long-term normal to supra-normal coagulation factor VIII activity in mouse models of hemophilia A and in non-human primates, representing a potential new treatment option for people with hemophilia A.”." (PMID 35508619, 2022). "Affected individuals have either reduced or absent levels of coagulation factor VIII and IX in plasma (hemophilia A and hemophilia B respectively)." (PMID 33407701, 2021). "Individuals with hemophilia A and B have respectively either reduced or absent levels of coagulation factor VIII and IX." (PMID 33407701, 2021). "Hemophilia is an X-linked hereditary bleeding disorder caused by a deficiency or lack of coagulation factor VIII (FVIII), which leads to hemophilia A (HA), or factor IX (FIX), which leads to hemophilia B (HB)." (PMID 33882996, 2021). "In F8 KO mice, the animal model of hemophilia A, CpG-ODN administration and consequent induction of IDO1 in dendritic cells (DCs) was shown to prevent generation of anti-FVIII antibodies while promoting FVIII-specific FoxP3+ Tregs, which effects required both IDO1 and AhR in host immune cells." (PMID 32351505, 2020). "Acquired hemophilia A (AHA) is a rare autoimmune disease with a clinically significant bleeding diathesis, resulting from circulating autoantibodies inhibiting coagulation factor VIII (FVIII)." (PMID 33121522, 2020). "Lack of coagulation factor VIII (FVIII) activity makes patients with haemophilia A unable to clot normally." (PMID 32290832, 2020). "Contrastingly, a CRISPR-Cas-mediated universal gene-correction knock-in strategy of introducing BDD-F8 gene at the endogenous F8 locus of hemophilia A patient-derived iPSCs differentiated into endothelial cells also did not yield optimal levels of FVIII." (PMID 32883366, 2020). "Deleterious substitutions of the F8 gene are responsible for causing hemophilia A, which is an inherited bleeding disorder resulting from reduced or absent activity of the coagulant protein factor VIII (FVIII)." (PMID 31876401, 2020).
hemophilia A (continued). "Coagulation factor VIII (FVIII) activity was less than 1% (normal range 60-150%), and a FVIII inhibitor was identified and quantified at 166 BU/mL to indicate a diagnosis of acquired haemophilia A (AHA)." (PMID 30937199, 2019). "To exclude the possibility of acquired hemophilia A, the measurement of antibodies to coagulation factor VIII is required, which we did not perform in this case." (PMID 29497641, 2015). "Hemophilia A (HA) is a bleeding disorder caused by lack of or a defective Factor VIII (FVIII) protein and results from defects in the Factor 8 (F8) gene." (PMID 23555096, 2013). "Hemophilia A (HA) is an X-linked genetic disorder caused by mutations in the Factor VIII (F8) gene, resulting in the lack of functional clotting protein Factor VIII (FVIII)." (PMID 41573577, 2025). "Hemophilia A (HA, MIM #306700) is an X-linked recessive bleeding disorder caused by a deficiency in coagulation factor VIII or lack of its function due to pathogenic variants in the F8 gene (MIM #300841)." (PMID 41465324, 2025). "Hemophilia A (HA) is the X-linked bleeding disorder that results from highly heterogeneous loss-of-function factor (F) VIII (FVIII) gene (F8) mutations and variably deficient-to-absent plasma FVIII coagulant activity (FVIII:C)." (PMID 40270541, 2025). "Hemophilia A (HA) and hemophilia B (HB) are rare heredity bleeding disorders that manifest in frequent and prolonged bleeding episodes and are caused by a lack of blood coagulation factor VIII (FVIII) or factor IX (FIX)." (PMID 33114325, 2020). "Nonetheless it must be highlighted that the X‐inactivation pattern in peripheral blood lymphocytes, in which F8 is not expressed, does not always readily explain the FVIII levels observed in individual carriers of hemophilia A (Orstavik, Scheibel, Ingerslev, & Schwartz, 2000)." (PMID 29490426, 2018). "However, int22h1/int22h2-mediated Xq28 duplication does not result in hemophilia A because a complete copy of F8 gene is preserved after formation of this duplication." (PMID 25927380, 2015). "To test the hypothesis that F8‐modified ProliHHs have therapeutic potential for the treatment of haemophilia A, we first confirmed that PHHs and ProliHHs do not express F8 through analysis of cellular transcriptional profiling, which was a prerequisite for the F8‐modified ProliHH therapy." (PMID 37199059, 2023). "In hemophilia A, which is characterized by a lack of coagulation factor VIII (FVIII), therapeutic measures include the transfusion of plasma or FVIII concentrates." (PMID 41445726, 2025). "Similarly, in the X-linked blood coagulation disorder hemophilia A, large mutations in the F8 gene and lack of central tolerance can result in the mounting of inhibitory anti-drug antibody (ADA) responses to the recombinant FVIII protein, which is administered as replacement therapy." (PMID 40666520, 2025).
hemophilia (326 papers, 2010 to 2026). Hemophilia is a genetic disorder characterized by spontaneous hemorrhage or prolonged bleeding due to factor VIII or IX deficiency. "Background and aim Hemophilia is a genetic bleeding disorder defined by a deficiency of coagulation factor VIII or IX, which results in recurrent bleeding episodes that frequently involve the joints." (PMID 42158789, 2026). "Hemophilia is an X-linked recessive inherited hemorrhagic disease primarily caused by reduced activity or deficiency of coagulation factor VIII (FVIII) or coagulation factor IX (FIX)." (PMID 41087175, 2025). "Hemophilia, an X‐linked recessive bleeding disorder, is caused by a deficiency of coagulation factor VIII (hemophilia A) or IX (hemophilia B) due to mutations in the genes encoding for these factors." (PMID 38713227, 2025). "HemA, a form of hemophilia caused by insufficient expression or gene mutation of coagulation factor VIII (FVIII), results in impaired blood clotting ability and can lead to life-threatening bleeding episodes, including intracranial hemorrhage." (PMID 39543114, 2024). "Haemophilia is caused by mutations in the genes encoding coagulation factor VIII (FVIII) or IX (FIX)." (PMID 38741157, 2024). "Hemophilia is a X-linked bleeding disorder due to the deficiency of coagulation factor VIII (hemophilia A) and IX (hemophilia B)." (PMID 38819423, 2024). "Hemophilia is a rare X-linked recessive inherited bleeding disorder caused by mutations of the genes encoding coagulation factor VIII (FVIII) or IX (FIX)." (PMID 36598583, 2023). "Initially associated with the life style of hemophilia, today we are faced with accumulating evidence that coagulation factor VIII is involved directly or indirectly in bone physiology." (PMID 35186990, 2022). "Hemophilia is an inherited bleeding disorder due to mutations in F8 or F9 genes encoding for factor VIII (FVIII) or factor IX (FIX) protein, respectively, which are necessary factors for proper blood coagulation and hemostasis." (PMID 35508619, 2022). "A very common well-known blood disease is hemophilia, a hematological disorder caused by mutations in the gene that codes for coagulation factor VIII or IX." (PMID 33987480, 2021). "Hemophilia is an inherited coagulation disorder characterized by deficiency of the coagulation factor VIII or IX." (PMID 31110621, 2019). "Acquired haemophilia is caused by autoantibodies against coagulation factor VIII (FVIII) that partially or completely inhibit its procoagulant function." (PMID 29804265, 2018). "Hemophilia, caused by deficiency or dysfunction of coagulation factor VIII (FVIII) or factor IX (FIX), is the most well-known hereditary bleeding disorder, with an incidence of one in every 5000 to 30,000 males worldwide." (PMID 27766048, 2016). "Haemophilia is an X linked congenital disorder which is caused by deficiency in the coagulation factor VIII (haemophilia A) or coagulation factor IX (haemophilia B)." (PMID 26431432, 2015). "Acquired hemophilia is caused by formation of an inhibitory antibodydirected against coagulation factor VIII." (PMID 24886030, 2014). "Haemophilia is a genetic bleeding disorder associated with a deficiency in the coagulation factor VIII." (PMID 24253479, 2013). "Hemophilia is a monogenic mutational disease affecting coagulation factor VIII or factor IX genes." (PMID 34299267, 2021). "Haemophilia is caused by deficiency in coagulation factor VIII or IX." (PMID 26431432, 2015). "However, disruption of X-linked genes encoding the interleukin-2 receptor (SCID model) or coagulation factor VIII (hemophilia model) caused neonatal death in cloned male pigs owing to infections and hemophilia." (PMID 23923039, 2013). "In order to assess the stability of LSEC-derived FVIII following liver growth, we administered GP64-LV.FVIII or VSV.G-LV.FVIII to newborn immune-competent hemophilia A mice (F8 KO)." (PMID 38684862, 2024).
hemophilia (continued). "Data collection included: age, severity of hemophilia, F8 genotype, FVIII inhibitor status with historical peak and titer at surgery, participation in a multinational clinical trial (HAVEN 1, Stasey or HAVEN 3) of emicizumab." (PMID 36983317, 2023). "The blood coagulation factor VIII indicated for hemophilia has traditionally been derived from human plasma fractions, but recombinant versions of the octocog alpha and beta and the lulioctocog alpha have been developed." (PMID 37239127, 2023). "Blood coagulation factor VIII and IX, which are indicated for hemophilia, have traditionally been derived from fractionated human plasma." (PMID 37239127, 2023). "The first-mentioned study was conducted in Arizona (USA)with a group of 30 adult patients with coagulation factor VIII or IX levels <5% (moderate hemophilia) and <1% (severe hemophilia)." (PMID 35743462, 2022). "Endothelial cells differentiated from corrected iPSCs expressed the F8 gene and functionally rescued factor VIII deficiency in a mouse model of hemophilia." (PMID 34485274, 2021). "Cloning of the F8 gene and cDNA by a group at Genentech in the 1980's launched a new era in hemophilia drug development." (PMID 32351497, 2020). "The hemophilia trait in women is recessive because a normal X chromosome is also present and responsible for at least a 50% level of coagulation factor VIII or factor IX." (PMID 28534860, 2017). "Turoctocog-α, a recombinant form of coagulation factor VIII (FVIII), which is used as another treatment for hemophilia, has a unique O-glycan on its B-domain suitable for glycoPEGylation." (PMID 26516849, 2015). "It was shown that different endothelial cells, i.e., lymphatic endothelial cells or glomerular endothelial cells express F8 but an increment in levels of F8 was observed in hemophilia patients after liver transplantation leading to the fact that the main contributor of plasma F8 is the liver." (PMID 38440189, 2024). "Over the last decade, the world of hemophilia has experienced an unprecedented therapeutic advance, thanks to the progress in bioengineering technologies, leading to the introduction of drugs with novel mechanisms of action based on restoring thrombin generation or coagulation factor VIII mimicking." (PMID 36297295, 2022). "Gene replacement therapy using adeno-associated virus (AAV) based vectors to deliver functional F8 and F9 genes to the liver have resulted in stable and therapeutic FVIII and FIX protein levels in adult hemophilia patients, with several candidates advancing into phase III clinical trials." (PMID 32670285, 2020). "Patients with large deletions in the F8 gene, or inversion mutation in intron 22 (I22I), have no circulating FVIII, suffer from severe hemophilia and are most likely to develop an adverse immune reaction to exogenous FVIII infusions." (PMID 29225598, 2017). "With the infusion of coagulation factor VIII and HAART, HIV infected hemophilia patient can be safety operation and may get effective result." (PMID 22937392, 2011).
bleeding disorder (151 papers, 2007 to 2026). "It is a rare and potentially life-threatening bleeding disorder caused by autoantibodies against coagulation factor VIII (FVIII), which causes increased clearance and neutralization of FVIII." (PMID 39307909, 2025). "Acquired haemophilia A (AHA) is a rare but potentially life-threatening bleeding disorder caused by autoantibodies against coagulation factor VIII." (PMID 40772167, 2025). "Acquired hemophilia A (AHA) is a life-threatening bleeding disorder caused by autoantibodies against coagulation factor VIII (FVIII)." (PMID 40861746, 2025). "Acquired hemophilia A (AHA) is a rare bleeding disorder caused by inhibitory autoantibodies against coagulation factor VIII (FVIII)." (PMID 39093750, 2024). "Acquired hemophilia A (AHA) is a rare bleeding disorder caused by the spontaneous development of neutralizing autoantibodies (inhibitors) directed against the endogenous coagulation factor VIII (FVIII)." (PMID 37893457, 2023). "Acquired haemophilia A (AHA) is a rare bleeding disorder caused by inhibitory autoantibodies against coagulation factor VIII (FVIII)." (PMID 36766524, 2023). "This bleeding disorder is caused by autoantibodies directed against the coagulation factor VIII (FVIII)." (PMID 37893457, 2023). "Acquired hemophilia A (AHA) is a bleeding disorder, autoimmune in nature, in which the body produces IgG antibody inhibitors that attack coagulation factor VIII, causing deficiency." (PMID 37736240, 2023). "Acquired haemophilia A (AHA) is a rare bleeding disorder caused by the development of autoantibodies which neutralize the activity of endogenous coagulation factor VIII (FVIII) and/or accelerate its clearance." (PMID 36010349, 2022). "Acquired hemophilia A (AHA) is a rare bleeding disorder caused by antibodies against coagulation factor VIII." (PMID 34434677, 2021). "Acquired hemophilia A (AHA) is a rare and severe bleeding disorder caused by the development of autoantibodies against coagulation factor VIII (FVIII)." (PMID 33424828, 2020). "Bleeding disorders such as HA and hemophilia B (HB), are X-linked genetic diseases cause by deficiency of coagulation factor VIII and coagulation factor (FIX), mainly due to genetic perturbations or variations in the F8 and F9 genes." (PMID 32443696, 2020). "Acquired hemophilia A (AHA) is a rare bleeding disorder caused by spontaneous development of autoantibodies directed against coagulation factor VIII (FVIII)." (PMID 24385759, 2013). "Given the physiological role of FVIII, where low levels of the protein result in a bleeding disorder, while high levels are associated with thrombosis, it is likely that miRNA-mediated F8 gene fine-tuning plays a particularly important role in maintaining homeostasis." (PMID 32850803, 2020). "Acquired hemophilia A (AHA) is a rare bleeding disorder related to autoantibodies, called inhibitors, acting against coagulation factor VIII (FVIII)." (PMID 40332156, 2025). "Acquired haemophilia A (AHA) is a rare severe bleeding disorder resulting from the production of autoantibodies directed against coagulation factor VIII." (PMID 35628847, 2022). "Generally, human coagulation factor VIII is one of the plasma derived valuable therapeutic proteins, administered in bleeding disorders and covers a remarkable market worldwide." (PMID 28979328, 2017). "Acquired hemophilia A (AHA) is a rare hemorrhagic disease in which autoantibodies against coagulation factor VIII- (FVIII-) neutralizing antibodies (inhibitors) impair the intrinsic coagulation system." (PMID 24741588, 2014). "Acquired hemophilia A (AHA) is a rare acquired bleeding disorder characterized by the presence of autoantibodies against coagulation factor VIII (FVIII) in the circulation, leading to reduced FVIII activity." (PMID 41909654, 2026). "In the case of the rare bleeding disorder hemophilia A (HA), miRNAs have been shown to directly target and down-regulate the F8 gene that codes for Factor VIII (FVIII)." (PMID 32443696, 2020).
thrombosis (71 papers, 2007 to 2025). "One is the F8 gene coding for the coagulation factor VIII, a known susceptibility gene for venous thrombosis." (PMID 35387445, 2022). "Coagulation factor VIII (FVIII) is an essential blood-clotting protein, and high levels of FVIII are reported to associate with increased risk of deep vein thrombosis and pulmonary embolism." (PMID 24982634, 2014). "In addition, procoagulant phospholipids (PPL), i.e. anionic phospholipids, mainly phosphatidylserine, and a high level of coagulation factor VIII (FVIII), which is an acute-phase protein, have been associated with an increased risk of thrombosis also including cancer patients." (PMID 34288927, 2021). "Coagulation factor VIII (FVIII) and fibrinogen as acute phase reactants are associated with a risk for thrombosis and its reoccurrence, especially in cancer patients.." (PMID 36419117, 2022). "The study also focused on VWF and F8 due to the strong role of the respective encoded proteins in the maintenance of hemostasis and thrombosis equilibrium and because increased VWF and FVIII levels have been already described as associated with an increased DVT risk." (PMID 34662354, 2021). "Therefore, vWA polymorphism may be involved in thrombosis disease owing to this gene that has a central role in blood coagulation systems and it is also the major mediator of platelet adhesion as well as the carrier for the coagulation factor VIII." (PMID 25250329, 2014). "Therefore, tests of FVL, coagulation factor VIII, antithrombin, and protein C are only recommended for patients with a thrombosis family history and who suffered from unexplained FRSA." (PMID 28798930, 2017).